NECTIN4 (nectin cell adhesion molecule 4)
Diseases named in the same sentence as NECTIN4 in open-access papers (continued):
Sharing a sentence is not in itself a finding about the gene and the disease.
tumor (continued). "Firstly, it could be related to the quantity of Nectin-4 expressed in tumor cells." (PMID 38755613, 2024). "Thus, treatment decisions for the metastatic stage could be based on NECTIN4 amplification status in primary tumor material, facilitating implementation into clinical trials." (PMID 38657187, 2024). "Furthermore, the blocked Nectin4 antibody can enhance tumour lethality in vitro and in vivo." (PMID 38170222, 2024). "The xenograft model bearing tumors derived from CLAC cells showed a decrease of tumor volume in response to the administration of rMV-SLAMblind as compared with the control group, suggesting that rMV-SLAMblind has an antitumor effect on a part of nectin-4-positive canine lung cancer cell lines." (PMID 37875555, 2023). "In addition, nectin‐4 might be a tumour growth factor in CPLA and thus is a promising biomarker for CPLA." (PMID 35905293, 2022). "In addition, this may lead to the study of tumour markers targeting nectin‐4 and the development of treatments with oncolytic virotherapy." (PMID 35905293, 2022). "Indeed, enfortumab vedotin, a kind of antibody–drug conjugates (ADCs) which targets NECTIN4, has been reported to suppress NECTIN4-overexpressing tumor cell growth and further evaluated preclinically in human breast, bladder, pancreas, lung, and urothelial cancers." (PMID 33478111, 2021). "CDV uses the signaling lymphocytic activation molecule (SLAM, or CD150) and nectin-4 (PVRL4) as entry receptors, well-known tumor-associated markers for several lymphadenomas and adenocarcinomas, which are also responsible for the lysis of tumor cells and apparent tumor regression." (PMID 32244946, 2020). "Interestingly, high Nectin-4 expression showed a significant association with lower tumor stage and negative lymph nodes." (PMID 31572728, 2019). "Our results demonstrated that Nectin-4 expression was significantly higher in cancer tissues compared with the adjacent normal tissues, and such up-regulation in cancer tissues was significantly correlated with advanced tumor stage and poorer prognosis of the EC patients." (PMID 31043861, 2019). "Overexpression of the measles virus (MV) receptor CD46 in many tumour cells may direct the virus to preferentially enter transformed cells and there is increasing awareness of the importance of nectin-4 and signaling lymphocytic activation molecule (SLAM) in oncolysis." (PMID 27782084, 2016). "Moreover, whilst MV receptor nectin-4 is expressed at low to moderate levels in respiratory epithelial cells, a number of studies have reported its abundant expression in lung, colon, ovarian and breast adenocarcinomas, making it a potential tumour marker." (PMID 27782084, 2016). "Therefore, we finally evaluated the role of Nectin-4 in tumor immunity." (PMID 25888293, 2015). "Therefore, Nectin-4 is a good target for these types of tumors, and thus, MV could be a good candidate tool to selectively attack tumor cells." (PMID 26317644, 2015). "CD3+ pan T cells were enriched and transduced with each of the NECTIN4-CAR lentiviral candidates, and anti-tumor activity against the RT112 human UC cell line was evaluated in co-culture assays." (PMID 40931013, 2025). "Nectin-4 regulates intercellular adhesion, remodels the actin cytoskeleton, triggers EMT, enhances the driving force for tumor cell pseudopodia extension, and ultimately leads to tumor development and metastasis." (PMID 40697656, 2025). "Here, we designed and evaluated the anti-tumor activity of multiple, second-generation CAR constructs targeting NECTIN4." (PMID 40931013, 2025). "Next, we tested the efficacy of systemic NECTIN4-CAR T cell therapy against EV resistant tumors and found that NECTIN4-CAR T cells retained highly potent, anti-tumor activity." (PMID 40931013, 2025). "Comparative analysis of Nectin‐4 and ABC transporter expression between non‐muscle‐invasive and muscle‐invasive primary tumours was possible in five cases." (PMID 39877564, 2025).
tumor (continued). "In contrast, significantly lower Nectin‐4 expression was detected in the Sq and SARC subtypes compared to pure NOS tumours, with only 15% (9/60) of Sq tumours and 17% (2/12) of SARC tumours exhibiting high Nectin‐4 expression (P = 0.035, 0.003)." (PMID 39801278, 2025). "The cohort included 14 NMIBC tumours (9 pure NOS, 2 MPUC, 1 Sq, 1 LELC, and 1 GL) with available Nectin‐4 expression data." (PMID 39801278, 2025). "TIGIT also binds poliovirus receptor-related protein 4 (PVRL4 or Nectin-4), a TIGIT-specific ligand recently known to be expressed on tumor cells." (PMID 40274631, 2025). "There was decreased expression of nectin-4 and increased expression of MDR1 in these metastatic sites compared to their expression on the primary tumor, respectively." (PMID 40225697, 2025). "In the present study, we examined the heterogeneity of membranous Nectin‐4 expression patterns within primary UBC, between primary tumour and metastatic LN sites, and across secondary histological and molecular subtypes." (PMID 39801278, 2025). "In conclusion, assessing Nectin‐4 expression in a large number of UBC samples, we observed low spatial heterogeneity within the primary tumour, while we found significantly higher expression in LN metastases." (PMID 39801278, 2025). "Novel pan-tumor targeting agents, such as TROP-2, Nectin-4, LAT1, GPC-1, and EphA2, are also under development, and clinical translation of radioligand therapy is anticipated." (PMID 40717183, 2025). "We also found that rosiglitazone increased NECTIN4 and HPGD in mice bearing HT1197 and UMUC-1 tumor xenografts." (PMID 40931013, 2025). "In our study, Cy7-labeled Nectin-4 NDC exhibits rapid systemic tissue distribution and a high level of tumor uptake in vivo, with an extended residence time at the tumor site compared to their retention in other organs." (PMID 38755613, 2024). "It differs from other ADCs targeting Nectin-4 by replacing MMAE, thereby changing the mechanism of tumor cell killing." (PMID 38606099, 2024). "In gastric and gallbladder cancers, Nectin-4 activates Ras-related C3 botulinum toxin substrate 1 (Rac1) through the PI3K/AKT pathway, promoting tumor proliferation and metastasis." (PMID 38606099, 2024). "After receiving a single dose of Nectin-4-MMAE, the group that received the combination treatment showed a significant decrease in tumor size compared to the group that received only one type of treatment." (PMID 38664366, 2024). "Nectin-4/PVRL4 is a transmembrane cell adhesion molecule that activates the PI3K/AKT pathway, promoting tumor angiogenesis and participating in the growth, dissemination, and migration of tumor cells." (PMID 38755613, 2024). "MV targets tumor cells through various receptors, including lymphocyte activation molecule 150 (CD150), lymphocyte activation molecule 46 (CD46), and Nectin cell adhesion molecule 4 (NECTIN-4)." (PMID 39697335, 2024). "In this study, we developed a novel Nectin-4-targeting Nb drug conjugate comprising two identical Nectin-4 Nbs, an HSA Nb, and vcMMAE, with homogeneous DAR, favorable affinity, and significant tumor uptake." (PMID 38755613, 2024). "The 15A7.5 mAb was chosen from a set of preselected anti-human nectin-4 antibodies, including clone 5A12.2, because of a lower EC50 value for cellular binding on keratinocytes than to tumor cell lines SUM190, T47D, and MDA-MB231-N4+." (PMID 39440991, 2024). "The combination of Nectin-4-MMAE and an autophagy inhibitor demonstrated enhanced antitumor effects in the HT1376 xenograft tumor model." (PMID 38664366, 2024). "Subsequently, we assessed the tumor cell-killing effect using CCK8 assays, revealing that Nectin-4 NDC exhibited approximately 60% inhibition against NCI-N87." (PMID 38755613, 2024). "TIGIT also binds PVRL4 (Nectin-4), a TIGIT-specific ligand almost exclusively expressed on tumor cells." (PMID 37345049, 2023).
tumor (continued). "After binding to Nectin-4 expressing cells, the ADC is internalized into the tumor cell, MMAE is released, and leads to apoptosis of the cell." (PMID 37480387, 2023). "High-expressing ERBB2 tumors have an increased expression of antibody drug conjugate (ADC) target genes NECTIN4 and TACSTD2 versus the low-expressing ERBB2 tumor." (PMID 38136267, 2023). "Previous studies have shown that GRHL3 can inhibit tumor growth and development in ESCC, while NECTIN4 and FZD2 play a role as cancer-promoting genes in ESCC, and no relevant report has been made on the role of other genes in ESCC." (PMID 37653730, 2023). "NECTIN4 also induces epithelial-to-mesenchymal transition (EMT), which contributes to the metastasis of tumor cells." (PMID 35256687, 2022). "The H&E staining and 11 IHC markers (Ki67, P63, GATA3, KRT5/6, KRT20, E-cadherin, 34βE12, PD-L1, EGFR, Nectin4, and HER2) were used to evaluate tumor phenotype maintenance." (PMID 35432811, 2021). "Many of the ADAM17 substrates, such as Nectin-4 and HB-EGF (heparin-binding epidermal growth factor-like factor) have already been investigated as potential tumor markers for ovarian cancer." (PMID 34771725, 2021). "NECTIN4 is known to activate the PI3K/Akt pathway, which regulates tumor cell proliferation and tumor growth." (PMID 33478111, 2021). "Nectin-4, UPAR, and FOLR-a are proteins expressed on the cell surface of the tumor, but can be cleaved by the action of proteases and shed into sera and other body fluids." (PMID 33413078, 2021). "Because of a better tumor molecular profiling, FGFR inhibitors, PARP inhibitors, anti-HER2 agents, and antibody drug conjugates targeting Nectin-4 are also emerging as new therapeutic options." (PMID 32498352, 2020). "Nectin 4 protein expression was assessed on 90 late stage (FIGO III/IV) HGSOC tissues by immunohistochemistry and scored according to percentage of positive tumor cells and staining intensities (H-score; 0, 1+, 2+, and 3+)." (PMID 31137558, 2019). "Therefore, the prognostic value of Nectin-4 may be dependent on the tumor type." (PMID 25888293, 2015). "In addition, our data suggest that Nectin-4 may contribute to tumor proliferation and angiogenesis." (PMID 25888293, 2015). "Although previous Nectin-4–targeted imaging studies provided insights into tumor heterogeneity, they have not yet explored drug-target interactions or dose-response dynamics." (PMID 41499516, 2026). "In contrast, NECTIN4 and TROP-2 displayed homogeneous expression patterns, with NECTIN4 being absent in approximately two-thirds of cases, while TROP-2 showed consistently strong positivity across tumor regions (98% 3+)." (PMID 41837391, 2026). "The other four patients had only weak or no Nectin‐4 expression in most of the analysed tumour samples (mean H‐Score ≤ 10)." (PMID 40847665, 2026). "In addition, tumor-to-blood (middle) and tumor-to-muscle (right) ratios mirrored these trends, further supporting the specificity of [68Ga]AJ647 for Nectin-4." (PMID 41499516, 2026). "The exclusion of eight T1 tumours (three Uro and five GU tumours) with available Nectin‐4 expression and molecular subtype data did not affect the results." (PMID 39801278, 2025). "On-target, off-tumor effects via Nectin-4 expression in skin Nectin-4 is not exclusively expressed in tumor cells." (PMID 40926943, 2025). "NECTIN4-CAR T cells exhibited dose-dependent cytotoxicity against RT112 cells over a range of effector to tumor cell (E:T) ratios compared to non-transduced (NTD) T cells from the same donor." (PMID 40931013, 2025). "Among these, cell adhesion molecules such as Nectin-2 (PVRL2) and Nectin-4 (PVRL4) have emerged as potential molecular candidates due to their roles in tumorigenesis, epithelial integrity, and immune modulation as tumor-specific ligands for the immune checkpoint receptor TIGIT." (PMID 40699695, 2025).
tumor (continued). "We also evaluated the combination with rosiglitazone in RT112 tumor xenografts using a second T cell donor as well as in HT1197 tumor xenografts, which are slower growing and express lower endogenous levels of NECTIN4." (PMID 40931013, 2025). "Additionally, in osteosarcoma, Nectin-4 directly downregulates the microRNA miR-520c-3p, activating the PI3K/AKT/NF-κB pathway and promoting tumor progression and metastasis." (PMID 40697656, 2025). "Comparison of Nectin‐4 and ABC transporter expression in non‐invasive and invasive primary tumours." (PMID 39877564, 2025). "The extracellular domain of Nectin-4 also interacts in cis with the prolactin receptor, which is essential for mammary follicle development, activating the JAK2–STAT5a signaling pathway, thereby regulating the growth of tumor cells." (PMID 40697656, 2025). "Our results demonstrate that enfortumab vedotin enters corneal epithelial cells via the Nectin-4-mediated on-target-off tumor mechanism and non-specific endocytosis." (PMID 40507807, 2025). "Among non-SCCs, only one primary tumor (<1 %) and none of the primary metastases or recurrent lesions had high NECTIN4 expression, yet the prevalence of tumors scoring 1+ was significantly highest in the recurrent lesions (p = 0.01)." (PMID 40577962, 2025). "EV is an ADC targeting Nectin-4, consisting of a fully human monoclonal antibody against Nectin-4 and monomethyl auristatin E (MMAE), which induces cell cycle arrest and apoptosis, leading to tumor cell death." (PMID 38898003, 2024). "Unlike in this setting, anti–NECTIN4 EV, whose therapeutic efficacy has been shown to depend on the expression of its target, is applied without previous tumor biomarker testing." (PMID 38657187, 2024). "They found that high expression of Nectin-4 protein was correlated with lower tumor stage, better overall survival (OS), and negative lymph nodes and predicted better outcomes in patients with TNBC." (PMID 38606099, 2024). "Additionally, tumor-to-blood (middle) and tumor-to-muscle (right) ratios mirrored these trends, further supporting the specificity of [68Ga]AJ647 for Nectin-4." (PMID 39763905, 2024). "EV targets nectin-4 to deliver the cytotoxic agent MMAE into cancer cells, where MMAE disrupts microtubule polymerization in keratinocytes, inducing apoptosis or necrosis and achieving a tumor-specific antitumor effect." (PMID 39712492, 2024). "Third, Nectin-4 expression was not evaluated and compared between primary tumor and metastatic organs." (PMID 39943993, 2024). "Membranous NECTIN4 expression of NECTIN4-amplified PRIM (median H-score, 290; range, 170-300) remained high in the corresponding MET (median H-score, 280; range, 20-300), except for the primary tumor, which lost its NECTIN4 amplification." (PMID 38657187, 2024). "In other tumor types beyond those where the ADC has been approved, higher expression of the TAA is also identified, like in BLCA, CESC, HNSCC, LUSC, PAAD, PRAD, and THCA for Trop2 and ESCA and SKCM for Nectin-4." (PMID 39684584, 2024). "For instance, in the therapeutic antibody-drug conjugate (ADC) enfortumab vedotin, the microtubule-disrupting agent monomethyl auristatin E (MMAE) was conjugated to the non-cytotoxic nectin-4-directed mAb AGS-22M6E to increase its tumor-killing effect." (PMID 38288120, 2023). "Only the level of urine Nectin-4, not serum Nectin-4, was correlated with the tumor H-score of Nectin-4, and there was a positive correlation between the level of urine Nectin-4 and serum Nectin-4." (PMID 37174031, 2023). "The level of urine Nectin-4, though not serum Nectin-4, was slightly correlated with the tumor H-score of Nectin-4 (Spearman’s ρ = 0.31, p = 0.044)." (PMID 37174031, 2023). "Urine levels correlated with tumor expression and serum levels in the Nectin-4 analysis, but not in the Nectin-2 analysis." (PMID 37174031, 2023). "We find colocalization of tumor regions in the H&E with expression of NECTIN4 across most H&E slides, regardless of treatment status." (PMID 35995947, 2022).
tumor (continued). "Compared with the mice treated with mUTD cells, Nectin4 mCAR-T therapy at low dosage had no significant anti-tumor effect, but prolonged survival and even cured two mice without recurrence at high dosage." (PMID 36479116, 2022). "Since Nectin-4 seems to be independent of tumor mass, it is at least partly expressed by tumor-surrounding tissues." (PMID 36497350, 2022). "However, there is veterinary literature indicating that an increase in tumour volume is a factor that worsens the prognosis of CPLA, so further analysis of nectin‐4 expression levels and prognosis is necessary." (PMID 35905293, 2022). "Overall, the expressions of NECTIN-4, TROP-2, and HER2 were associated with histologic subtypes, but not to age, year, gender, tumor diameter, tumor location, and TNM grade (Supplementary 2)." (PMID 35515131, 2022). "Recent studies reported that Nectin-4 firstly combined with afadin and then regulated the actin cytoskeleton remodeling, which could induce EMT and enhance pseudopod driving force in tumor cell lines." (PMID 35953862, 2022). "By targeting Nectin-4, EV delivers MMAE directly to the tumor cells." (PMID 36686762, 2022). "Due to the usage of Nectin-4 tumor marker and not the ubiquitously expressed CD46 receptor for infection, wild type strain MV has gained attention as a potentially suitable targeted oncolytic agent." (PMID 33406633, 2021). "Moreover, for ADAM17 substrates such as Nectin-4 and HB-EGF, it was shown that increased levels contribute to tumor proliferation." (PMID 34771725, 2021). "Furthermore, antibody blockade of nectin-4 suppresses human tumor growth in SCID mice transplanted with human NK cells, while nectin-4 overexpression in human tumor cells led to increased tumor growth in the presence of human NK cells." (PMID 34367161, 2021). "Nectin-4 is attractive as an ADC target because studies have shown that it is overexpressed in several tumor types but nearly absent in normal adult tissues." (PMID 34358100, 2021). "Correlation of Nectin 4 protein expression to tumor spread types, miliary and non-miliary, was not possible as this information is not available from this cohort of patients." (PMID 31137558, 2019). "Because rMV-SLAMblind does not have an affinity for immune cells, rMV-SLAMblind likely reaches Nectin-4-expressing tumor cells by blood flow but not through the spread of the virus-infected immune cells." (PMID 26317644, 2015). "Expression of Nectin-4 in tumor cell lines varied according to the origin of the tumor: No expression was detected in leukemic cells." (PMID 17474988, 2007). "Nectin-4 is indeed not detected in normal breast epithelial cells, and highly expressed both in tumor cell lines and tumors from breast origin." (PMID 17474988, 2007). "Mice exhibiting low Nectin-4 engagement posttreatment showed reduced tumor growth inhibition, regardless of dose, suggesting that TE itself may serve as a more reliable early biomarker of therapeutic efficacy than dose or Nectin-4 expression alone." (PMID 41499516, 2026). "By leveraging the specificity of [68Ga]AJ647 for Nectin-4, we demonstrated the ability to dynamically quantify TE across a range of preclinical models, bridging critical gaps in current ADC development strategies and enabling a deeper understanding of drug-tumor interactions." (PMID 41499516, 2026). "Sc/NE tumours showed only negative or weak Nectin‐4 expression (P = 0.019)." (PMID 39801278, 2025). "These regimens can be administered regardless of nectin-4 expression on tumor specimens." (PMID 40072062, 2025). "Finally, given that NECTIN4 is expressed on the normal skin epithelium as well as on normal bladder urothelial cells, we sought to evaluate potential on-target, off-tumor toxicity of the NECTIN4-CAR T cells." (PMID 40931013, 2025).